ROCK1 (Rho associated coiled-coil containing protein kinase 1)
Diseases named in the same sentence as ROCK1 in open-access papers (continued):
Sharing a sentence is not in itself a finding about the gene and the disease.
hepatocellular carcinoma (28 papers, 2011 to 2025). A malignant tumor that arises from hepatocytes. "ROCK1 is closely associated with NF-κB activity under different conditions, such as hepatocellular carcinoma, pulmonary fibrosis, and arthritis-induced brain cognitive impairment." (PMID 34399695, 2021). "Again, in hepatocellular carcinoma cells, inhibition of the Rho-associated coiled coil-containing protein kinase 1 (ROCK1) attenuated an EMT expression profile and the process of VM." (PMID 27608016, 2016). "Having determined that mutating the caspase cleavage site in ROCK1 promoted necrosis-like inflammatory cell death during acute chemically induced liver damage and in hepatocellular carcinomas, we examined whether similar effects would be induced by pharmacological ROCK inhibition." (PMID 36497425, 2022). "miR-506 inhibits hepatocellular carcinoma (HCC) cell proliferation and tumorigenicity by targeting Rho-associated protein kinase 1 (ROCK1), which is upregulated in HCC tissues and inversely correlated with miR-506 levels, supporting miR-506 mimics as a therapeutic strategy." (PMID 40248198, 2025). "DEN-treated Rock1 NC mice had fewer hepatocellular carcinoma (HCC) tumours than Rock1 WT mice, and Eμ-Myc; Rock1 NC mice lived significantly longer than Eμ-Myc; Rock1 WT mice." (PMID 38616733, 2024). "miR-31 has been reported to regulate apoptosis and invasion of hepatocellular carcinoma HepG2 cells through the ROCK1/F-actin pathway." (PMID 36782118, 2023). "As reported, salidroside can regulate Rho/ROCK1/NF-κB pathway to ameliorate arthritis-induced brain cognition deficits and microRNA-145 can inhibit proliferation and promote apoptosis of hepatocellular carcinoma through downregulation of ROCK1/NF-κB pathway." (PMID 32546278, 2020). "It is demonstrated that LncRNA DANCR /miR-27a-3p axis can regulate EMT via ROCK1/LIMK1/COFILIN1 pathway in hepatocellular carcinoma progression." (PMID 31638991, 2019). "miR-494-3p was further shown to target ROCK1, while miR-122 has been demonstrated to modulate RhoA and influence motility of hepatocellular carcinoma cells." (PMID 29343687, 2018). "Moreover, recent data highlighted the indirect inhibitory effect of Api on ROCK-1 expression in hepatocellular carcinoma models in vivo and in vitro as well as the upregulatory effect on BDNF in kindled mice models." (PMID 36943623, 2023). "The upregulated ROCK1 can reverse the suppressive effects of miR-506 in hepatocellular carcinoma." (PMID 34874810, 2021). "Thus, ROCK1 protein levels and activity are increased in the liver of mice on a high-fat diet (HFD), BCAA metabolism has been linked to insulin resistance and T2D, and the STE20-type kinases MST3 and MST4 have been linked to the progression of hepatocellular carcinoma." (PMID 40231468, 2025). "Hepatocellular carcinoma (HCC) tumours in ROCK1nc mice had more neutrophils and CD8+ T cells relative to mice expressing wild-type ROCK1, indicating that spontaneous tumour cell death also was more immunogenic." (PMID 36497425, 2022). "Notably, in hepatocellular carcinoma, GLIPR1 activates the PI3K/PDK1/ROCK1 signaling axis, thereby enhancing EMT, cellular motility, and resistance to 5-fluorouracil." (PMID 41208460, 2025).
colorectal cancer (25 papers, 2011 to 2025). A primary or metastatic malignant neoplasm that affects the colon or rectum. "A higher level of Rho-associated coiled coil-containing protein kinase 1 (ROCK1), which is considered a major miR-148a target, plays a crucial role in the development of colorectal cancer." (PMID 35743255, 2022). "Three somatic mutations were identified in ROCK1 that result in activating C-terminal truncations and polymorphisms in both ROCK1 and ROCK2 have been associated with colorectal cancer development." (PMID 32309283, 2020). "Proliferation and metastasis abilities can be suppressed by miR-199a-5p in colorectal cancer via ROCK1 targeting." (PMID 31409775, 2019). "Two ROCK1 and five ROCK2 polymorphisms were found significantly associating with colorectal cancer development." (PMID 26725045, 2016). "ROCK1 is a candidate gene involved in microsatellite instability (genetic instability due to problems with DNA mismatch repair) also correlated with colorectal cancer development." (PMID 26725045, 2016). "Additionally, studies have shown that IRX5 can negatively regulate RhoA/ROCK1/LIMK1 signaling pathway to promote the metastasis of colorectal cancer cells." (PMID 34486491, 2021). "TFAP2C inhibits Hippo signaling by upregulating ROCK1 and ROCK2 in colorectal cancer, thereby contributing to the stemness of colorectal cancer cells and the resistance to 5‐FU." (PMID 37799806, 2023). "Results showed that ROCK1, LIMK1, MMP3, and MMP9 mRNA expressions were down-regulated after ALKAL1 silencing in colorectal cancer RKO and SW480 cells." (PMID 33391411, 2021). "In addition, Stadler S has demonstrated that ROCK1 and ROCK2 paly an essential role in the metastasis of colorectal cancer." (PMID 37062850, 2023).
diabetes (25 papers, 2013 to 2026). "Through this approach, we uncovered a previously unrecognized role of hUCMSCs in modulating metabolic reprogramming and EndMT and identified the Tgfb1i1/Rock1 axis as a key regulator driving the loss of endothelial characteristics in diabetes." (PMID 41535231, 2026). "While RAGE deletion did not alter systemic glucose homeostasis or lipid levels, it effectively attenuated diabetes-associated vascular stress, particularly through the inhibition of the Rho-associated coiled-coil-containing protein kinase 1 (ROCK1) pathway." (PMID 40806443, 2025). "Similarly, systemic ROCK1-deficient mice show improved kidney outcomes in streptozotocin-induced diabetes, with partial protection against albuminuria and tubulointerstitial fibrosis." (PMID 41311514, 2026). "Moreover ROCK1-deficient mice with diabetes less develop diabetic nephropathy, and podocyte-specific constitutive active ROCK1 murine model deteriorated kidney dysfunction." (PMID 32661376, 2020). "Overall, the L-CA-ROCK1 phenotype demonstrates a possible causal role of hepatic ROCK1 overactivity in metabolic disease pathologies, identifying a potential therapeutic target in liver ROCK1 to treat obesity and diabetes." (PMID 33633690, 2020). "Furthermore, emerging evidence suggests ROCK1 is a molecular mediator underlying the pathogenesis of diabetes and obesity." (PMID 33633690, 2020). "Additionally, elevated ROCK1 activity consistently is associated with various metabolic disease states, suggesting ROCK1 may be useful as a preclinical marker of diabetes and obesity." (PMID 33633690, 2020). "Our study extends the current understanding by demonstrating that hUCMSCs attenuate diabetes-induced EndMT through suppression of the Tgfb1i1/ROCK1 pathway." (PMID 41535231, 2026). "Intriguingly, our current study demonstrated that 5-HT4R activation not only inhibits the diabetes-induced upregulation of MLCK and ROCK1 but also restores the downregulation of TJ proteins in the colon in diabetes." (PMID 37766457, 2023). "Interactions between miRNAs and ROCK1 have been assessed in different disorders, including metabolic syndrome, diabetes, acute lung injury, endometriosis, LPS-induced lung endothelial hyperpermeability and pneumonia." (PMID 36177350, 2022). "In this context, it is relevant that we found ed-NGF treatment also resulted in a decrease in microvessel fragmentation in STZ, and reduced expression of Rock1, a marker of endothelial cell dysfunction, as well as Müller cells in diabetic retina." (PMID 36291113, 2022). "In the past, dysregulated ROCK1 level has been reported in many metabolism-related disorders, including obesity, diabetes, and NAFLD." (PMID 34446693, 2021). "The exposure of podocytes to high glucose results in a significant elevation of ROCK1 activity, indicating a potential role for ROCK1 in the podocytopathy seen in diabetes." (PMID 33150249, 2020). "For example: IGF1, IGF2 and LEPR, which have previously been associated with diabetes, while STAT5B and ROCK1 have shown weaker associations to the disease." (PMID 32735660, 2020). "Rho-kinase 1 (ROCK1) has been implicated in diverse metabolic functions throughout the body, with promising evidence identifying ROCK1 as a therapeutic target in diabetes and obesity." (PMID 33633690, 2020). "In humans, VL ROCK1 activity positively correlates with glucose disposal in lean subjects, while insulin-stimulated ROCK1 activity is impaired in those with diabetes or obesity, possibly due to elevated levels of the ROCK1 antagonist RhoE." (PMID 33633690, 2020). "Additional genes include members of the JAK/STAT signaling pathway, e.g. STAT5B or ROCK1, where it has been argued that this pathway is dysregulated in metabolic diseases including obesity and diabetes." (PMID 32735660, 2020). "In recent years, ROCK1-targeting treatment strategy has drawn much attention for its promising clinical application in cancer therapy, diabetes, stem cell biology, and so on." (PMID 31263414, 2019).
diabetes (continued). "Diabetes induced a striking change in ROCK-1 subcellular distribution, displaced from the cytoplasm to the membrane, co-localizing with F-actin and responsible for the apical cellular constriction." (PMID 28821742, 2017). "But, the early consequences of diabetes on ROCK-1-induced cytoskeleton regulations remain imperfectly understood." (PMID 28821742, 2017). "In contrast, ROCK1 has detrimental effects on mitochondrial function and cellular energy metabolism in diabetes." (PMID 27411515, 2016). "In order to demonstrate a role of ROCK isoforms in diabetes-induced vascular dysfunction, we first examined the protein levels of ROCK1 and ROCK2 in both endo(−) and endo(+) aortic rings from both groups of rats (respectively)." (PMID 23530857, 2013). "Collectively, our findings reveal a novel molecular mechanism through which hUCMSCs may reduce the inflammatory microenvironment via interactions with Tgfb1i1 and Rock1, thereby mitigating EndMT progression and aortic remodeling in diabetes." (PMID 41535231, 2026). "In podocytes—highly specialized cells with limited regenerative capacity—ROCK1-driven mitochondrial dysfunction leads to energetic failure and oxidative damage, contributing to the onset of albuminuria, a hallmark of CKD in people with diabetes." (PMID 41311514, 2026). "In the present study, we investigated whether 5-HT4R activation ameliorates diabetes-driven TJ barrier dysfunction by inhibiting MLC phosphorylation mediated by either MLCK or ROCK1." (PMID 37766457, 2023). "However, the limitation of the current study is that we did not provide direct evidence that 5-HT4R activation protects the TJ barrier against diabetes by limiting the MLCK/ROCK1-pMLC signaling pathways." (PMID 37766457, 2023). "Diabetes increased ROCK1, and genetically removal of ROCK1 alleviated kidney injury." (PMID 34889040, 2022). "The results of that study implicate ROCK1 as a critical regulator of the mitochondrial dynamics in diabetes and suggest that ROCK1 may be a relevant therapeutic target for the generation of oxidative stress in podocytes." (PMID 33101039, 2020). "Interestingly, we also discovered that ROCK1 rs8089974 and rs35996865 were protective factors in the midst of diabetics." (PMID 28184030, 2017). "Moreover, it was shown that ROCK1 KO mice treated with streptozotocin to induce diabetes were protected against the development of albuminuria, which is a typical sign of kidney dysfunction in diabetes." (PMID 26635606, 2015). "Interestingly, reduced ROCK1 expression was more effective in preventing diabetes-induced changes than ROCK2." (PMID 26635606, 2015). "The current study showed that T1D led to the downregulation of TJ proteins and upregulation of MLCK, ROCK1, and p-MLC, suggesting that disrupted TJ assembly induced by MLCK/ROCK1-p-MLC signaling pathways may contribute to the downregulation of TJ proteins in the colon in diabetes." (PMID 37766457, 2023). "Furthermore, stimulation of 5-HT4R inhibits diabetes-induced upregulation of myosin light chain kinase (MLCK), Rho-associated coiled coil protein kinase 1 (ROCK1), and phosphorylated myosin light chain (p-MLC), which are key molecules that regulate TJ integrity, in the colonic mucosa of WT mice." (PMID 37766457, 2023). "Chronic treatment with RS67333 dramatically inhibited diabetes-induced upregulation of MLCK, ROCK1, and pMLC in colonic mucosa compared to the control." (PMID 37766457, 2023). "Our results suggest that 5-HT4R activation protects the TJ barrier against diabetes, possibly by limiting the MLCK/ROCK1-pMLC signaling pathways." (PMID 37766457, 2023). "STAT5B and ROCK1 are members of the JAk/STAT pathway, which has recently been shown to influence processes relevant for obesity and diabetes." (PMID 32735660, 2020).
diabetes (continued). "Although not all genetic variants in RhoA and ROCK1 genes were proved to be related to overall risk of PCa, we further conducted subgroup analysis stratified by age, smoke status, Pack-years of smoking, drink status, tea drinking, family history of cancer, hypertension and diabetes." (PMID 28184030, 2017). "In contrast, in similar haploinsufficient ROCK1+/– and ROCK2+/– KO mouse lines a decrease in blood pressure under basal conditions and an attenuation of the diabetes-induced blood pressure increase was observed." (PMID 26635606, 2015). "The major findings of this study were that diabetes led to an upregulation in ACE, ROCK1, ROCK2, and omega-hydroxylase proteins and a downregulation in ACE2 protein that was accompanied by abnormal vascular reactivity in the rat CC." (PMID 25309930, 2014). "Up-regulation of arginase was reduced in haploinsufficient diabetic ROCK1 and ROCK2 mice, which could explain the attenuation of diabetes-induced vascular endothelial dysfunction and improvement in vascular function during diabetes." (PMID 26635606, 2015). "STZ still led to increases in the protein levels of MLCK, ROCK1, and p-MLC in the colonic mucosa compared to vehicle treatment, but RS67333 did not block the diabetes-induced increases in the protein levels of MLCK, ROCK1, or p-MLC in the colonic mucosa of 5-HT4R KO mice." (PMID 37766457, 2023).
ovarian carcinoma (25 papers, 2014 to 2025). A malignant neoplasm originating from the surface ovarian epithelium. "Therefore, our microarray analysis data reminded that the high LINC00452 expression-associated aggravation in RFS of ovarian cancer might be at least partially attributed to derepression of ROCK1 gene." (PMID 33168781, 2020). "NEAT1 can upregulate the expression of TJP3, MEST, and ROCK1 in ovarian cancer cell lines, subsequently promoting the progression of ovarian cancer." (PMID 36011001, 2022). "Other authors have shown that knockdown of RBP4 significantly reduces ovarian cancer cell migration and proliferation driven through the RhoA/Rock1 and extracellular signal-regulated kinase (ERK) pathways." (PMID 32156052, 2020). "For instance, it was reported that lncRNA NEAT1 promotes ovarian cancer cell metastasis through regulation of miR-382-3p/ROCK1 axis." (PMID 33168781, 2020). "To validate our bioinformatics analytical data from ovarian cancer tissues, we determined the expression profiles of miR-501-3p and ROCK1 in different ovarian cancer cells." (PMID 33168781, 2020). "We provided solid bioinformatic and experimental data revealing the novel LINC00452/miR-501-3p axial controlling of ROCK1 expression in ovary cancer cells." (PMID 33168781, 2020). "Our results indicated that RBP4 can drive ovarian cancer cell migration and proliferation via RhoA/Rock1 and ERK pathway." (PMID 29642915, 2018). "To test whether there was LINC00452-related post-translational regulation of ROCK1 in ovarian cancer, we first conducted an in-silico prediction through catRAPID the probability of any physical interaction between LINC00452 and ROCK1 protein." (PMID 33168781, 2020). "In addition, it was also reported that ROCK1 could regulate the Warburg effect and accelerated ovarian cancer growth." (PMID 36774349, 2023). "And through the correlation analysis of the expressions of ECT2 and RHOA, ROCK1, and ROCK2 in ovarian cancer samples in TCGA database, it was found that the expression of ECT2 was significantly positively correlated with RhoA, ROCK1, and ROCK2." (PMID 40655948, 2025). "In ovarian cancer cells, the inhibition of miR-1244 promotes proliferation and aerobic glycolysis (PKM2, HK2, and PDK1) and ROCK1 expression." (PMID 38338859, 2024). "So far, our results had suggested that LINC00452 acts as a miR-501-3p sponge controlling ROCK1 expression and subsequently the outcome of RFS in ovarian cancer patients." (PMID 33168781, 2020). "The association between RBP4 and tumor size suggests that RBP4 may promote tumor growth, as also described in ovarian cancer, where RBP4 enhances migration and proliferation by activating RhoA/Rock1 and ERK pathways and upregulating MMP2 and MMP9." (PMID 41007818, 2025). "Moreover, RhoA/Rock1 pathway activation and upregulation of CyclinD1 were involved in RBP4-induced ovarian cancer cell migration." (PMID 38913193, 2024). "Multiple putative miRNA targets of NEAT1 and the downstream proteins have been proposed to contribute to the oncogenic roles of NEAT1 in ovarian cancer, such as the NEAT1/miR-1312/TJP3, NEAT1/miR-506, NEAT1/let-7 g/MEST/ATGL, NEAT1/miR‐382‐3p/ROCK1, and NEAT1/miR-365/FGF9 axes." (PMID 37986114, 2023). "Among the targets regulated by miR-124, we could isolate at least six genes (PDCD6, ROCK1, SLUG, STAT3, TGF-β, ZEB1) common to several epithelial cancers, including lung, stomach, hepatocellular, breast, and ovarian cancers." (PMID 36362406, 2022). "Additionally, RBP4, identified as a serum marker for ovarian cancer, directly induces cancer progression of ovarian cancer cells by increasing the expression of the cancer metastasis factors MM2 and MM9 through the RhoA/Rock1 pathway." (PMID 34068244, 2021).